HSFX1 (heat shock transcription factor family, X-linked 1)
Synonyms: LW-1
Tractability: PROTAC: UniProt records ubiquitination sites on it; ubiquitination databases record sites on it.
Gene: Protein-coding gene on chromosome X (149,774,068 to 149,776,867, forward strand). Ensembl gene ENSG00000171116.
Subcellular location: Nucleus; Cytoplasm
Subcellular location (Human Protein Atlas): Nucleoplasm; Cytosol; Plasma membrane
Gene Ontology:
Molecular function: protein binding; DNA-binding transcription factor activity, RNA polymerase II-specific; RNA polymerase II cis-regulatory region sequence-specific DNA binding; DNA-binding transcription factor activity; sequence-specific DNA binding
Biological process: regulation of transcription by RNA polymerase II; regulation of DNA-templated transcription
Cellular component: cytosol; nucleus; chromatin; cytoplasm
Homologues: Orthologues: chimpanzee HSFX2 (98% identical), Caenorhabditis elegans hsf-1 (12% identical), Drosophila melanogaster Hsf (12% identical). Paralogues in human: HSFX2 (100% identical), HSFY1 (28% identical), HSFY2 (28% identical), HSF5 (19% identical), HSF1 (16% identical), HSFX3 (15% identical), HSFX4 (15% identical), HSF4 (14% identical), HSF2 (13% identical).